ENSG00000257264 (microRNA 3179-1)
Gene: Long non-coding RNA gene on chromosome 16 (14,901,499 to 14,902,174, forward strand). Ensembl gene ENSG00000257264.
Gene Ontology:
Biological process: miRNA-mediated post-transcriptional gene silencing
Cellular component: RISC complex